CATSPER2 (cation channel sperm associated 2)
Description:
Pore-forming subunit of the CatSper complex, a sperm-specific voltage-gated calcium channel, that plays a central role in calcium-dependent physiological responses essential for successful fertilization, such as sperm hyperactivation, acrosome reaction and chemotaxis towards the oocyte.
Tractability: Small molecule: it belongs to a druggable protein family. Antibody: its Gene Ontology location is reachable by antibodies, with high confidence; UniProt predicts a signal peptide or a membrane-spanning region. PROTAC: ubiquitination databases record sites on it.
Gene: Protein-coding gene on chromosome 15 (43,628,503 to 43,668,118, reverse strand). Ensembl gene ENSG00000166762.
Subcellular location: Cell projection, cilium, flagellum membrane
Subcellular location (Human Protein Atlas): End piece; Plasma membrane; Primary cilium; Principal piece; Vesicles
Pathways (Reactome):
Reproduction: Sperm Motility And Taxes
Gene Ontology:
Molecular function: protein binding; voltage-gated calcium channel activity; calcium-activated cation channel activity; monoatomic ion channel activity
Biological process: calcium ion transport; fertilization; flagellated sperm motility; sperm capacitation; spermatogenesis; calcium ion transmembrane transport; monoatomic cation transmembrane transport; monoatomic ion transmembrane transport; monoatomic ion transport; transmembrane transport
Cellular component: sperm principal piece; CatSper complex; plasma membrane; membrane
Genetic constraint (gnomAD): Loss-of-function variants: 53 observed, 63.62 expected, observed/expected ratio (o/e) 0.83, 90% interval 0.67 to 1.05. The upper end of that interval is the gene's LOEUF score, 1.05, which puts it in group 4 of 6, group 1 being the genes least tolerant of losing a copy. Missense variants: 560 observed, 611.79 expected, observed/expected ratio (o/e) 0.92, 90% interval 0.85 to 0.98. Synonymous variants: 196 observed, 221.93 expected, observed/expected ratio (o/e) 0.88, 90% interval 0.79 to 0.99.
Homologues: Orthologues: chimpanzee CATSPER2 (97% identical), dog CATSPER2 (79% identical), pig CATSPER2 (79% identical), rabbit CATSPER2 (75% identical), mouse Catsper2 (69% identical), rat Catsper2 (68% identical), macaque CATSPER2 (34% identical). Paralogues in human: SCN2A (28% identical), SCN3A (28% identical), SCN5A (28% identical), SCN4A (28% identical), SCN8A (28% identical), SCN1A (28% identical), SCN9A (28% identical), CACNA1A (26% identical), SCN10A (26% identical), SCN11A (26% identical), CACNA1B (25% identical), CACNA1D (25% identical), and 14 more.
Diseases named in the same sentence as CATSPER2 in open-access papers:
CATSPER2 is named in the same sentence as 21 diseases in open-access papers, as found by Europe PMC text mining. Sharing a sentence is not in itself a finding about the gene and the disease. The quoted sentences say what the papers report.
deafness (18 papers, 2018 to 2025). An inherited or acquired condition characterized by the complete loss of the ability to hear from one or both ears. "Homozygous deletion of both STRC and CATSPER2 has been reported to be associated with deafness-infertility syndrome (OMIM: 61102)." (PMID 35248088, 2022). "For instance, 4 male children had homozygous multigene deletion that involved STRC and CATSPER2, placing them at increased risk of deafness-infertility syndrome, which causes HL and infertility." (PMID 36166228, 2022). "The initial identification of syndromic male infertility (SMI) in relation to CATSPER2 mutations was documented in a French family, where certain members exhibited a multifaceted phenotype encompassing infertility, deafness, and Congenital Dyserythropoietic Anemia type 1 (CDA1)." (PMID 39469589, 2024). "One such example is the contiguous gene deletion of CATSPER2 and STRC genes, previously associated with deafness‐infertility syndrome (DIS) in males." (PMID 38884051, 2024). "The characteristic feature of syndromic male infertility is the presence of mutations in the genetic locus encompassing the CATSPER2 gene, along with neighboring genes like STRC (stereocilin), which have been implicated in deafness." (PMID 39469589, 2024). "In Family 44, a homozygous deletion involving STRC and CATSPER2, leading to deafness–infertility syndrome (OMIM #611102), was identified through GS utilizing our newly developed analytic pipeline." (PMID 40225913, 2024). "Catsper2 is also involved in deafness (Deafness-Infertility-Syndrome, DIS) suggesting that the functions of different subunits are not limited to sperm cells only." (PMID 38970681, 2024). "A partial genomic deletion of CATSPER2 was initially described in a French family presenting with a deafness-infertility syndrome (DIS) with asthenozoospermia, followed by the identification of full deletions of the gene in three unrelated Iranian families." (PMID 35409285, 2022). "Contiguous gene deletion syndrome on chromosome 15q15.3, including STRC and CATSPER2, as identified in patient 15, is responsible for a deafness-infertility syndrome." (PMID 34440452, 2021). "Interestingly, deletions or mutations in Catsper2 gene have been associated with patients with the deafness‐infertility syndrome (DIS) or non‐syndromic male infertility, highlighting the importance of Catsper2 gene in human male fertility." (PMID 36345591, 2022). "Further analysis of these 11 families for deafness associated infertility genes such as FOXI1, CATSPER2 and STRC could possibly throw more light on the etiology of this phenotype." (PMID 29921236, 2018). "STRC deletions are reported in approximately 1% of mixed deafness populations, making it as a major contributor to congenital hearing impairment, and can cause autosomal recessive NSHL or Deafness-infertility syndrome (DIS) in males if the adjacent CATSPER2 gene is also involved in the deletion." (PMID 30622556, 2018). "In the sample of patients with NSHL, syndromes such as Pendred syndrome (six in the SLC26A4 gene), deafness, and male infertility syndrome (DIS) (three males and two females with NSHL with bi-allelic gross deletions in the STRC and CATSPER2 genes) were also found." (PMID 36555390, 2022).
Infertility (17 papers, 2014 to 2024). "Next, we set out to unravel the pathomechanism underlying the infertility of CATSPER2–/– patients and OI, IUI, and IVF failure, which almost certainly rests on the failure of sperm to penetrate the egg coat." (PMID 38165034, 2024). "It has been described that CATSPER1 and CATSPER2 mutations in human sperm are associated with infertility." (PMID 37108159, 2023). "In mice, congenital ablation of CatSper1, CatSper2, CatSper3 or CatSper4 genes inhibits CatSper currents and sperm hyperactivation and causes infertility, although spermatogenesis and initial motility are unaffected." (PMID 37108159, 2023). "Interestingly, men harboring mutations or deletions on CatSper1- or CatSper2-encoding genes are infertile, and sperm samples from men undergoing ARTs present diminished responses to Pg compared to control samples from normozoospermic men." (PMID 33374265, 2020). "Further, the clinical importance of the chromosomal deletion in the region harboring STRC to CATSPER2 is associated with not only hearing loss but also infertility in males, referred to as deafness infertility syndrome, due to the fact that CATSPER2 plays essential roles in sperm motility." (PMID 30867468, 2019). "Consequently, the disruption of CATSPER2 could potentially be the underlying cause of significantly reduced sperm motility in patients suffering from infertility." (PMID 39469589, 2024). "Studies in human patients have been able to detect several deletions and/or mutations in different CATSPER subunits, i.e., CATSPER1, CATSPER2, CATSPER3 or CATSPERE and their association with infertility." (PMID 37108159, 2023). "Further, in sperm from a proven father heterozygous for the deletion of CATSPER2 (CATSPER2+/–), CatSper-mediated membrane currents as well as motility parameters were unaffected, supporting fully penetrant autosomal-recessive inheritance of CATSPER2-related infertility." (PMID 38165034, 2024). "This demonstrates that the infertility phenotype was caused by the homozygous deletion of CATSPER2 alone rather than by deletion of STRC and/or CKMT1B." (PMID 38165034, 2024). "Here, using CatSper-deficient sperm from infertile patients lacking the CATSPER2 gene, we show that Ca2+ responses evoked by reproductive steroids and prostaglandins rest invariably on Ca2+ influx via CatSper." (PMID 34381781, 2021). "Using a CatSper2-deficient infertile patient, no remaining cation current was recordable, when both Hv1 and KSper were blocked." (PMID 29963982, 2018). "Genetic analysis of infertile men primarily from consanguineous families with clustering of male-factor infertility, indeed, identified individuals with nonsense variants in the CATSPER1 or CATSPER3 genes as well as with a homozygous deletion of CATSPER2 and the contiguous gene STRC." (PMID 38165034, 2024). "Moreover, the infertility phenotype of patients with homozygous deletion of CATSPER2 (patient C5), homozygous deletion of CATSPER2 combined with heterozygous deletion of STRC and CKMT1B (patients C6–C8), or homozygous deletion of CATSPER2, STRC, and CKMT1B (patients C1–C4) was indistinguishable." (PMID 38165034, 2024). "Likewise, CatSper1 or CatSper2 null mouse spermatozoa exhibits a decreased sperm motility, abnormal flagellar beating, as well as lacked hyperactivity and acrosome reaction, thus leading to the complete infertility of knockout male mice 4, 40-42." (PMID 33456575, 2021). "To confirm that the currents induced by DEFB1 and CCL20 were genuinely mediated by CatSper channel, we performed patch-clamp experiments on sperm samples donated by an infertile male who carries a G to C mutation of CatSper2 in one allele and complete absence of CatSper2 in the other allele." (PMID 29207656, 2017).
Infertility (continued). "Additionally, because the STRC gene region is associated with a segdup that results in pseudogenes of both STRC and CATSPER2, homozygous deletions of the entire region (STRC and CATSPER2) cause DIS, characterized by mild SNHL in males and females and sperm motility defects and infertility in males." (PMID 24963352, 2014).
male infertility (13 papers, 2013 to 2025). The inability of the male to effect fertilization of an ovum after a specified period of unprotected intercourse. "The CATSPER2 gene, which is involved in “capacitation, hyperactivation, acrosomal reaction and sperm motility”, has been linked to male infertility." (PMID 41254778, 2025). "In particular, our recent study found that the copy number variation of CATSPER2 causes idiopathic male infertility with normal semen parameters." (PMID 37754226, 2023). "Mutations of CATSPER1 and CATSPER2 genes have been related to male infertility in humans, and genetic deletion of any of the Catsper genes (CATSPER 1-4) resulted in loss of hyperactivated motility during the time of capacitation in mice." (PMID 32155986, 2020). "Further, the deletion of chromosome 15q15.3 from STRC to CATSPER2 is also known to be a genetic cause of deafness infertility syndrome (DIS), which is associated with not only hearing loss but also male infertility, as CATSPER2 plays crucial roles in sperm motility." (PMID 35022556, 2022). "Consequently, patients with a STRC deletion might also possess a CATSPER2 deletion that could be involved in hearing loss and male infertility." (PMID 30867468, 2019). "Genetic heterogeneity is one cause of homozygous copy number variants (CNVs) involving the CATSPER2 and STRC genes, which are associated with DIS and male infertility." (PMID 41254778, 2025). "In a rat model of CP-induced male infertility, TS effectively restored sperm count, motility, testosterone levels, and the expression of Catsper1, Catsper2, Catsper3, and Catsper4." (PMID 37754226, 2023). "Deletions or mutations in the Catsper2 gene are associated with the deafness‐infertility syndrome (DIS) and non‐syndromic male infertility." (PMID 36345591, 2022). "In those patients for whom we used the modified version of our panel that includes the CATSPER2 gene, we identified its involvement in 10/13 cases with STRC deletion, suggesting that DIS is likely an under-diagnosed cause of hearing loss and male infertility." (PMID 24963352, 2014). "Further, the deletion of chromosome 15q15.3 from STRC to CATSPER2, is also known to be a genetic cause of deafness infertility syndrome (DIS: OMIM 611,102), which is associated with not only hearing loss but also male infertility, as CATSPER2 plays crucial roles in sperm motility." (PMID 35022556, 2022). "Sensorineural hearing loss and male infertility (Deafness-Infertility Syndrome; DIS) is a contiguous gene deletion syndrome resulting from homozygous deletion of the CATSPER2 (responsible for male infertility) and STRC (responsible for hearing loss) genes on chromosome 15q15.3." (PMID 23648117, 2013).
deafness-infertility syndrome (12 papers, 2013 to 2025). Deafness-infertility syndrome (DIS) is a very rare syndrome associating sensorineural deafness and male infertility. "CatSper activity in human sperm cells is apparently independent of the cAMP/PKA-signaling pathway, as described using CATSPER2 gene deletion in deafness-infertility syndrome (DIS)." (PMID 37762052, 2023). "The gene CATSPER2, a neighboring gene to STRC, is responsible for sperm motility and leads to deafness infertility syndrome in males, most commonly with sequential deletion of both STRC and CATSPER2 genes." (PMID 36504663, 2022).
hearing loss (5 papers, 2014 to 2025). "In the evaluation of CNV, one copy number alteration residing in STRC and CATSPER2, which are both known hearing loss genes, was detected by both EXCAVATOR2 and in-house CNV tool from only SB246–482." (PMID 29482514, 2018).
asthenozoospermia (4 papers, 2017 to 2022). "In our study we have reported a decrease in CatSper1 and CatSper2 gene expression by asthenozoospermia and teratozoospermia groups." (PMID 29492471, 2017).
hyperthyroidism (1 paper, 2020). Overactivity of the thyroid gland resulting in overproduction of thyroid hormone and increased metabolic rate. "Considering CATSPER2 in the hyperthyroidism group, the severity of the immunohistochemical staining of the head, middle piece of the sperms was moderate, while that of the tail of the spermatozoa was obtained as low." (PMID 32923926, 2020). "The present study was conducted to investigate the effect of hyperthyroidism on the expression of CATSPER1 and CATSPER2 genes in the seminiferous tubules of mice." (PMID 32923926, 2020). "According to the importance of cation channel (CATSPER1 and CATSPER2) in motility and the function of sperm, the aim of the present study was to investigate the effect of hyperthyroidism on the expressions of CATSPER1 and CATSPER2 genes in the seminiferous tubules of mice." (PMID 32923926, 2020). "In our study, not only the expression rates of both CATSPER1 and CATSPER2 genes were not significantly different between the hyperthyroidism and control groups, but also the immunohistochemically reactions of anti- CATSPER1 and CATSPER2 antibodies between the two groups." (PMID 32923926, 2020). "As the findings of the present study indicated, hyperthyroidism has no significant changes in the expressions of both CATSPER1 and CATSPER2 genes." (PMID 32923926, 2020).
melanoma (1 paper, 2014). A malignant, usually aggressive tumor composed of atypical, neoplastic melanocytes. "For example PPIP5K1->CATSPER2 and YARS2->NAP1L1 have been predicted in melanoma samples." (PMID 25133550, 2014).
oligoasthenoteratozoospermia (1 paper, 2017). A form of male infertility that is characterized by a combination of low number or oligozoospermia, poor motility or asthenozoospermia, and abnormal shape or teratozoospermia of sperms. "The gene expression of CatSper1 revealed an increase by oligozoospermia and oligoasthenoteratozoospermia groups where as CatSper2 gene expression revealed no significant change by oligozoospermia and oligoasthenoteratozoospermia groups." (PMID 29492471, 2017).
varicocele (1 paper, 2023). A condition characterized by the dilated tortuous veins of the spermatic cord with a marked left-sided predominance. "Decreased CATSPER2 mRNA expression in BPA-exposed offspring testis could affect sperm functions since the level of CATSPER2 mRNA expression was significantly downregulated in varicocele-induced rats." (PMID 36835180, 2023).
CATSPER2 also shares sentences with these, for which no sentence is quoted: Bloom syndrome (2 papers); congenital ichthyosis (2); alcohol dependence (1); Azoospermia (1); cancer (1); hereditary spastic paraplegia type 11 (1); Hypertension (1); Pendred syndrome (1); Tay-Sachs disease (1); teratozoospermia (1); tumour (1).